CXCL9 (C-X-C motif chemokine ligand 9)
Diseases named in the same sentence as CXCL9 in open-access papers (continued):
Sharing a sentence is not in itself a finding about the gene and the disease.
breast cancer (continued). "CXCL9 was significantly expressed at high levels in 15 unique analyses in breast cancer and 21 unique analyses in lymphoma." (PMID 34439306, 2021). "In this study, we sought to investigate the potential value of CXCL9 according to immune responses in patients with breast cancer (BC)." (PMID 34527583, 2021). "To analyze the role of these chemokines in metastasis, we implanted MDA breast cancer cells co-expressing CXCL9 and CXCL10 bilaterally into the fourth mammary fat pads of female, nonobese, diabetic-severe combined immunodeficiency gamma (NSG) mice." (PMID 32198421, 2020). "Oncomine database revealed that mRNA expressions of CXCL9/10/11 were significantly higher in human breast cancer than in normal tissues in multiple datasets and transcription levels of CXCL1/2/4/5/7 were prominently low." (PMID 32963527, 2020). "Here, the authors show that CXCR3-expressing breast cancer cells secrete IL-1 to induce a paracrine crosstalk with fibroblasts in the lung, which involves CXCL9/10 production and results in colonization of the lung." (PMID 32198421, 2020). "The results suggested that CXCL9/10/13 expressions were significantly associated with infiltrating levels of B cells, CD8+ T cells, CD4+ T cells, neutrophils, and DCs in breast cancer, while CXCL12 was conversely correlated with macrophages." (PMID 32963527, 2020). "Our study showed high CXCL9/10 expression significantly correlated with favorable survival outcome in breast cancer." (PMID 32963527, 2020). "The transcriptional levels of CXCL9/10/11/13 in breast cancer tissues were significantly elevated while the transcriptional levels of CXCL1/2/3/12 were decreased based on intersections of Oncomine database and GEPIA." (PMID 32963527, 2020). "CXCL13, originally named B cell attracting chemokine 1, is also identified to be correlated with CXCL9 (rho = 0.52, p < 0.001) in early breast cancer." (PMID 32963527, 2020). "The inducible overexpression of PTPN2 not only repressed IFNγ‐induced p‐STAT‐1 and Cxcl9/10 expression, but most importantly also the recruitment of PTPN2‐deficient CAR T cells to HER‐2‐E0771 mammary tumours in vivo." (PMID 31803974, 2020). "Our findings suggest a model in which JNK activity in metastasis-initiating breast cancer cells induces expression of IL-1α/β, which interact with IL-1R on lung fibroblasts to stimulate NF-κB-mediated induction of Cxcl9/10." (PMID 32198421, 2020). "Denkert's study showed that high CXCL9 expression conferred a significantly increased pathologic complete response rate (pCR) in breast cancer patients who received neoadjuvant anthracycline/taxane‐based chemotherapy." (PMID 32963527, 2020). "Stimulation of MDA-LM2, SUM-LM1, and primary patient-derived breast cancer cells with recombinant CXCL9 and/or CXCL10 increased oncosphere formation, and this was reversed by addition of CXCR3i." (PMID 32198421, 2020). "Our own studies indicate that the deletion of PTPN2 in CAR T cells drives the expression of CXCR3 and the trafficking of CAR T cells to CXCL9/10‐expressing mammary tumours." (PMID 31803974, 2020). "We find that breast cancer cells that have invaded the lungs secrete interleukin 1 alpha/beta (IL-1α/β) to induce the chemokines CXCL9/10 in MAFs." (PMID 32198421, 2020). "Specifically, IL-1α and IL-1β secreted by breast cancer cells induce CXCL9 and CXCL10 production in lung fibroblasts via NF-κB signaling, fueling the growth of lung metastases." (PMID 32198421, 2020). "For example, CXCL10 affects the tumor microenvironment and plays important role in breast cancer progression, CXCL9 is identified as a biomarker in breast cancer." (PMID 31874629, 2019). "Evidence for the role of CXCL9 in attracting NK and cytotoxic T cells was shown in a murine model of breast cancer." (PMID 30319622, 2018). "We knocked down C/EBP-β by siRNA treatment, which reduced IL-6 and CXCL9 expression induced by miR-155 inhibition in two breast cancer cell lines." (PMID 26848978, 2016).
breast cancer (continued). "Metastatic breast cancer cells expressed chemokines that can direct the recruitment of T lymphocytes (CXCL9, CCL2 or CX3CL1)." (PMID 25882816, 2015). "A scoring method, comprising a combination of Fibronectin1 and CXCL9 serum concentrations, has shown a remarkable increase in detection (up to 54%) from ER-negative cases in breast cancer." (PMID 24278236, 2013). "In breast cancer,tumor cell expression of the chemokines CXCL9 and 10 recruits lymphocytes, improvessurvival in mouse models and human studies, and PGE2 inhibits expression of both chemokines in breastcancer cells in vitro." (PMID 24004819, 2013). "CXCL9 overexpression in breast cancer cells increases T cell infiltration, decreases tumor growth and prolongs survival of immunocompetent but not immunocompromised mice." (PMID 23408142, 2013). "To find out if this holds true for CXCL9 as well, we performed immunohistochemical analyses of primary breast cancer tissue sections using a monoclonal antibody to CXCL9." (PMID 22333315, 2012). "In human breast cancer, CXCL9 mRNA overexpression correlates with the number of tumor infiltrating lymphocytes and predicts response to different chemotherapeutic regimens." (PMID 22333315, 2012). "CXCL9 was visualized in breast cancer specimens by immunohistochemistry, expression levels of CXCL9 and cyclooxygenases were determined by ELISA and western blotting, respectively." (PMID 22333315, 2012). "By this approach we show that CXCL9 is localized predominantly in the cytoplasm of breast cancer cells." (PMID 22333315, 2012). "Inverse correlation of COX expression and intratumoral CXCL9 concentration in human breast cancer samples indicate the relevance in vivo." (PMID 22333315, 2012). "We observed an inverse correlation between COX-2 overexpression and intratumoral CXCL9 concentration and a trend towards lower CXCL9 expression in COX-1 overexpressing breast cancer tissues." (PMID 22333315, 2012). "In human breast cancer, we and others have shown that a high expression of the CXCL9 mRNA correlates with an increased number of infiltrating lymphocytes and a better response to chemotherapy." (PMID 22333315, 2012). "In agreement with this, we see a decrease in mammary tumor cell seeding following cell injection, an increase in apoptosis and enhanced formation of ROS and the cytokine CXCL9." (PMID 21884585, 2011). "The injection of a mammary tumor cell line stably expressing CXCL9 cDNA into mice resulted in smaller tumors as well as fewer lung metastases." (PMID 21884585, 2011). "Functional assays using microfluidic devices and degranulation tests revealed that lactate-exposed NK cells exhibited reduced chemotaxis and diminished cytotoxicity against MCF-7 and MDA-MB-231 breast cancer spheroids, accompanied by decreased CXCL9 and CXCL10 production." (PMID 41896548, 2026). "Only KTR14, KRT16, CXCL9, and CFD in BRCA1 Ovarian Cancer and TSPAN7 and CDKN2C in BRCA2 ovarian cancers were highly upregulated, and KANK4, MFGE8, LINC00346, and SA100A1 in BRCA1 mutated breast cancer, and MAGEA4 in BRCA2 breast cancers." (PMID 40647506, 2025). "This suggests that the infiltration of CXCL9 + macrophages and T_NK cells may be beneficial to breast cancer patients’ survival, with a potential reciprocal relationship between them." (PMID 41325308, 2025). "Finally, in vitro experiments confirmed that CXCL9 + macrophages inhibited the viability of breast cancer cells." (PMID 41325308, 2025). "Finally, our in vitro experiments demonstrated that the knockdown of CXCL9 in M1 macrophages attenuates their inhibitory effect on breast cancer cells." (PMID 41325308, 2025). "Finally, experiments were conducted to validate the effects of CXCL9 + macrophages on breast cancer cells." (PMID 41325308, 2025). "Additionally, it revealed a cooperative effect between IFN-γ and TNF-α in inducing the production of CCL5 and CXCL9 from breast cancer cells." (PMID 38167224, 2024).
breast cancer (continued). "Additionally, CXCL9 is a potential clinical biomarker in ER-negative and triple-negative breast cancer." (PMID 39770478, 2024). "We next addressed whether cytokines produced during trastuzumab-dependent NK cell-activation could stimulate CXCL9/10 production from bystander breast cancer cells in in vitro coculture assays." (PMID 38167224, 2024). "To date, there have been limited studies on CXCL9 and breast cancer." (PMID 38957805, 2024). "Another niche study of fibroblasts in metastases found that IL-1α and IL-1β secreted by breast cancer cells induced CXCL9 and CXCL10 production in lung fibroblasts, which was also achieved through NF-κB signaling and ultimately promoted the progression of lung metastasis." (PMID 36759842, 2023). "Meta-analyses of transcriptomic data revealed that chemokine (C-X-C module) ligand 13 (CXCL13) within the CXCL9 module of the chemosensitive (pCR) model is one of the most robust predictors of favorable disease outcome for breast cancer patients treated with neoadjuvant chemotherapy." (PMID 35911770, 2022). "Taken together, these results suggest that miR-155 in breast cancer cells enhances CXCL9/10/11 expression by suppressing SOCS1 expression and tilting the p-STAT1/p-STAT3 ratio, leading to the recruitment of effective T cells to the tumor site and subsequently an improved antitumor immune response." (PMID 35925680, 2022). "It has been demonstrated that CXCL9-expressing tumor cells reduced tumor growth and lung metastases and prolonged survival via the recruitment of natural killer (NK) cells and T cells in murine breast cancer models." (PMID 35725915, 2022). "In addition, SRC-3 inhibition by SI-2 and SRC-3 KD increased C-X-C motif chemokine ligand 9 (Cxcl9) expression in breast cancer to recruit C-X-C motif chemokine receptor 3 (Cxcr3)-expressing cytotoxic immune cells into breast tumors." (PMID 36316775, 2022). "Indeed, STAT3 inhibition by Stattic phenocopied miR-155 overexpression and enhanced CXCL9 production in breast cancer cells." (PMID 35925680, 2022). "Moreover, the results from the Human Protein Atlas suggested that higher CXCL9 expression correlated with better OS prognosis in breast cancer (P<0.01)." (PMID 34527583, 2021). "Taken together, CXCL9 could be a new innate immune checkpoint for breast cancer therapy and immunotherapy." (PMID 35052427, 2021). "In order to further probe whether CXCL9 is a potential biomarker for immune response for breast cancer, we examined the relationship between CXCL9 and a panel of recognized immune biomarkers and targets." (PMID 34527583, 2021). "In summary, CXCL9 significantly correlated with the prognostic of breast cancer and immune cell infiltration and could be innate immune checkpoint for breast cancer immunotherapy." (PMID 35052427, 2021). "Furthermore, we further performed molecular docking analysis to identify small molecular drug of target CXCL9 for breast cancer immunotherapy." (PMID 35052427, 2021). "Finally, we performed immunohistochemistry with breast cancer tissue samples and observed that CXCL9 is highly expressed in the ER-negative subgroup and positively correlated with the immune-related factors LAG3, PD1, PDL1 and CTLA4 to varying degrees." (PMID 34527583, 2021). "This suggests that CXCL9 may be a predictor of prognosis in certain molecular subtypes of breast cancer." (PMID 34527583, 2021). "CXCL9 has been identified as a candidate biomarker in breast cancer." (PMID 32963527, 2020). "In conclusion, our study found additional evidence that CXCL9/10/12/13 could be used as potential prognosis biomarkers in breast cancer." (PMID 32963527, 2020). "Ultimately, interruption of the CXCL9/10-CXCR3-mediated paracrine loop through systemic inhibition of JNK or CXCR3 represents a potential future strategy to inhibit metastatic colonization of the lungs in basal-like breast cancer." (PMID 32198421, 2020).
breast cancer (continued). "We considered whether breast cancer cells may be a direct source of IL-1 ligands to induce CXCL9/10 in MAFs." (PMID 32198421, 2020). "Notably, ectopic expression of CXCL9/10 significantly promoted growth of mammary tumors and lung metastasis." (PMID 32198421, 2020). "Since IL-1α/β are secreted cytokines, we investigated whether CM of cultured breast cancer cells drives induction of CXCL9/10 in fibroblasts in vitro." (PMID 32198421, 2020). "CXCL-9 was increased in both breast cancer and in dense breast tissue suggesting that among an upregulation of pro-inflammatory cytokines other may balance the net results of the inflammatory response of the tissue." (PMID 29387062, 2017). "In the role of early cancer detection, the elevated CXCL9 concentrations in blood samples of patients with early breast cancers (compared to those of normal volunteers) indicated that CXCL9 could be a screening blood marker for breast cancers." (PMID 24278236, 2013). "Our immunohistochemical breast cancer studies localize CXCL9 to cancer cells." (PMID 22333315, 2012). "Furthermore, in a mouse model transfection of murine breast cancer cells with CXCL9 increases chemotactic T cell recruitment, impairs tumor growth, prevents lung metastasis formation, and prolongs survival." (PMID 22333315, 2012). "In human breast cancer samples, CXCL9 concentrations correlate inversely with COX-2 expression." (PMID 22333315, 2012). "Subsequently we tested whether the COX-2 specific inhibitor celecoxib would also raise CXCL9 or CXCL10 release from MCF-7 or MDA-MB 231 breast cancer cells." (PMID 22333315, 2012). "However, it should be noted that contradictory results are also reported with regard to CXCR3 expression and survival of human breast cancer patients likely due to the reported expression of CXCR3 on breast cancer cells which can promote CXCL9/10-mediated motility." (PMID 37055433, 2023). "Finally, whether CXCL9 can be determined as a new prognostic checkpoint for breast cancer immunotherapy remains to be further verified." (PMID 35052427, 2021). "Notably, we find that the chemokine receptor CXCR3, that binds CXCL9/10, is specifically expressed in a small subset of breast cancer cells, which exhibits tumor-initiating ability when co-transplanted with fibroblasts and has high JNK signaling that drives IL-1α/β expression." (PMID 32198421, 2020). "In the literature, elevated expression of CXCL9 and IL7R was related to an improved breast cancer prognosis." (PMID 40725191, 2025). "For instance, B3GNT7 and CTSV predicted detrimental prognosis in BRCA2-mut breast cancers, and CD6, CXCL9, and CXCL13 predicted favorable outcomes in BRCA1-mut ovarian cancers." (PMID 40647506, 2025). "Using this strict approach, we selected two genes associated with a detrimental prognosis: B3GNT7 and CTSV in BRCA2-mut breast cancers, and three with a favorable prognosis: CD6, CXCL9, and CXCL13 in BRCA1-mut ovarian cancers." (PMID 40647506, 2025). "CXCL9, also referred to as monokine induced by IFN-γ (MIG) and induced by IFN-γ, appeared to be the highest overexpressed molecule among the CXCL9, -10, −11/CXCR3 axis found in the primary breast cancer samples that developed brain metastasis." (PMID 39262976, 2024). "The CXCL-9,-10,-11/CXCR3 axis, dependent on IFN-γ signaling activity, was overexpressed in primary breast cancer samples of patients who developed brain metastasis." (PMID 39262976, 2024). "Trastuzumab-induced NK cell activation against SKBR3, BT474 and HC1954 HER2-positive breast cancer cells resulted in the secretion of CCL5, IFN-γ and the consequent production of CXCL9 and CXCL10, as analysed by ELISA in cell-free coculture supernatants." (PMID 38167224, 2024). "We also identified a prognostic role for immune activation characterized by immune-related genes such as chemokine (CXCL9) and cytotoxic granules (GNLY) in HER2-positive early stage breast cancer." (PMID 35954313, 2022).
breast cancer (continued). "A more detailed analysis of 1100 patients with breast cancer (BRCA) revealed significant positive correlations between Il12b, Ifng, Ccl4, Ccl5, Cxcl9, and Cxcl10 gene expression levels and tumor infiltration of CD8+ T cells and M1 macrophages." (PMID 34446712, 2021). "Several differentially expressed mRNAs in HER2-positive breast cancer (including CXCL2, CXCL12, CXCL10, CXCL11, CXCL9 and CXCL14) were enriched in the biology processes of chemokine receptor binding and chemokine activity." (PMID 34257572, 2021). "Subsequently, the educated CAFs then secrete CXCL9/CXCL10 to stimulate CXCR3 on breast cancer cells, thereby maintaining the cancer stemness of breast cancer cells to promote lung metastatic colonization." (PMID 33407730, 2021). "In total, the results strongly suggested CXCL9, CCR7, and SOCS1 played an important role in chemo-resistance of breast cancer." (PMID 32974144, 2020). "Once secreted from fibroblasts, CXCL9 and CXCL10 bind to CXCR3 on the surface of a subpopulation of breast cancer cells to complete a paracrine loop that promotes initiation and growth of metastasis in the lungs." (PMID 32198421, 2020). "For example, CCL2, CCL5, CXCL8, and CXCL12 can promote breast cancer, while CXCL9, CXCL10, and CCL16 can inhibit breast cancer." (PMID 32253815, 2020). "CXCR3+ breast cancer cells express high levels of IL-1α/β via JNK signaling, suggesting that they can both induce CXCL9/10 in MAFs and benefit from these chemokines." (PMID 32198421, 2020). "Combined overexpression of CXCL9/10 in MDA and SUM parental breast cancer cells significantly increased their ability to form spheres when cultured under serum-free low adhesive conditions." (PMID 32198421, 2020). "In line with this, we observed a significant correlation between CXCL9/10 and IL1A/B expression in dissected metastases samples from breast cancer patients." (PMID 32198421, 2020). "In order to confirm the biological functions of CXCL9, CCR7, and SOCS1 in breast cancer, the plasmids for overexpressing CXCL9, CCR7, and SOCS1 were transfected into MCF-7/T cells." (PMID 32974144, 2020). "More importantly, the mRNA expressions of CXCL9, CCR7, and SOCS1 in breast cancer cells were observed notably higher in the taxanes-sensitive cell lines (MCF-7 and BCap37) than taxanes-resistant cell lines (MCF-7/T and Bads-200)." (PMID 32974144, 2020). "All the outcomes strongly confirmed that CXCL9, CCR7, and SOCS1 screened out via WGCNA participated in the regulation of taxanes-sensitivity in breast cancer cells." (PMID 32974144, 2020). "The results indicated that the expression levels of CXCL9, CXCL10, CXCL11, and CXCL13 were marked higher in breast cancer tissues than in normal tissues, while the expression levels of CXCL1, CXCL2, CXCL3, and CXCL12 were lower inversely." (PMID 32963527, 2020). "In conclusion, our study shed light on clinical theragnostic relationships between miR-335-5p/CXCL9, let-7c-5p/CCR7/SOCS1 axes, and taxanes-resistance in breast cancer." (PMID 32974144, 2020). "Of them, CXCL10, CXCL9, CCL11, CCR8, and GNG13 up-regulate breast cancer, while the other genes download-regulate breast cancer." (PMID 31874629, 2019). "In contrast, CXCL9 has been shown to predict good outcomes for cancer patients; HCAR3 and GNG4 exhibit suppressor effects on the process of tumorigenesis in mammary cancer and in GBM." (PMID 31469863, 2019). "In breast cancer cell lines, Prostaglandin E2 (PGE2) impaired IFN-γ mediated CXCL9 and CXCL10 release." (PMID 30319622, 2018). "For example, unfractionated heparin inhibits IFN-γ-induced CXCL9 and CXCL10 production by human breast cancer cells dose-dependently." (PMID 29379506, 2017). "We further examined IL-6 and CXCL9, as IL-6 is a well-known target whereas the CXCL9 is uncharacterized target of the C/EBP-β in breast cancer." (PMID 26848978, 2016).